TNFRSF9 (TNF receptor superfamily member 9)
Diseases named in the same sentence as TNFRSF9 in open-access papers (continued):
Sharing a sentence is not in itself a finding about the gene and the disease.
tumor (continued). "TNFRSF9, also known as CD137, is found on activated T cells and plays an important role in tumour immunotherapy." (PMID 35392242, 2022). "Tumor-infiltrating T cells significantly upregulated well-established co-stimulatory and inhibitory receptors TNFRSF9 (CD137, 4-1BB) and HAVCR2 (TIM-3)." (PMID 35874727, 2022). "Further heterogeneity has been reported within Tregs present in the tumor, which is characterized by the expression of activation molecules such as TNF receptor superfamily member 9 (TNFRSF9) and Interleukin 1 receptor type 2 (IL1R2)." (PMID 36032082, 2022). "We found potential immunotherapy targets, for example, ACP5, MAGEH1, TNFRSF9 and CCR8 for tumor infiltrating Tregs and MT1 for exhausted CD8+ T cells (CD8+ Tex cells)." (PMID 35562760, 2022). "LAYN+ Tregs showed highly expressed LAYN, TNFRSF9, and ICOS, but the proportion of this cell population in tumor‐infiltrating cells was very small, which was different from FOXP3+ Tregs." (PMID 35474948, 2022). "Among the 18 Treg-specific overlapping genes, ACP5, MAGEH1, TNFRSF9 and CCR8 were exclusively expressed in tumor-infiltrating Tregs and are potential immunotherapy targets for tumor-infiltrating Tregs." (PMID 35562760, 2022). "In situ, the combined detection of TNFRSF9, TNF, and IFNG identified most of the tumor-specific reactive TIL repertoire." (PMID 34707600, 2021). "For example, CD4+ naive T cells (cluster 0/cluster 2) located at the core of the tumor expressed more immune checkpoint molecules, such as CTLA4, LAG3, HAVCR2, and TNFRSF9/CD137." (PMID 34513820, 2021). "CD137, also known as 4-1BB or tumor necrosis factor (TNF) receptor superfamily member 9 (TNFRSF9) is pivotal for immune homeostasis and tumor suppression." (PMID 34512655, 2021). "We found that the exhausted CD8+ T cells located in the core of the tumor had a higher expression of immune checkpoint molecules, including PDCD1, CTLA4, LAG3, TNFRSF9/CD137, CD27, and HAVCR2." (PMID 34513820, 2021). "Conversely, we found GAD_CD14 derived signature being positively correlated with the expression of ITGAE (CD103) and TNFRSF9 (CD137) genes, which represent activated tumor-specific T-cells." (PMID 33193316, 2020). "In HCC, we observed increased expression of several more activation- (IFNG, CD38, IL2RA, TNFRSF9) and exhaustion-related (TIGIT, CTLA4, PDCD1, ENTPD1) genes in tumor MAIT cells." (PMID 32849590, 2020). "Ligation of co-stimulatory T cell receptors, such as OX40 (Tnfrsf4, CD134), 4-1BB (Tnfrsf9, CD137) and GITR (Tnfrsf18, CD357), with agonist mAbs has been shown to augment the anti-tumor immune response in numerous cancer models." (PMID 25411639, 2014). "Within the Treg population, we identified a unique subset of tumor-infiltrating TNFRSF9 (4–1BB) Tregs49 that increased in the non-solid and solid lesions." (PMID 39803458, 2025). "In addition, the expression of some tumor-related inflammatory factors, such as CDCP1 and TNFRSF9, are upregulated in AAA." (PMID 40599317, 2025). "Interestingly, we observed marked upregulation of a series of immune checkpoints (e.g., CD86, CD80, HAVCR2 and LGALS9) in most tumor infiltrating myeloid cells, and a unique pattern in TAMs (e.g., NECTIN2, TNFRSF14, CD276 and TNFRSF9)." (PMID 38414027, 2024). "Previous studies reported that upregulation of IFN-γ (gene name, IFNG) and 41BB (gene name, TNFRSF9) expression on activated T cells could be applied to recognize and isolate tumour-specific T cells." (PMID 38727812, 2024). "Key differentially expressed genes included PTGS2 (pro/antitumor), FOSL1, TNFRSF9, IL1B, DIO2, and PHLDA1 (antitumor), along with under-expressed genes with pro-tumor effects that may inhibit proliferation." (PMID 39409923, 2024). "The expression of activation-specific genes (IFNG, GZMB, and TNFRSF9) and cell proliferation-specific genes (IL2, IL2RA, and CD28) decreased with the increasing rounds of tumor stimulation, especially from round 2 (the round in which tumor-killing ability begins to decline)." (PMID 39657666, 2024).
tumor (continued). "However, the expression of genes participating in AP (e.g., HLA‐DRA/DMB and CD74) and anti‐tumour immunity (e.g., GBP1, IFNG and TNFRSF9) were significantly higher in the TS, while genes involved in angiogenesis (e.g., VEGFA) was significantly higher in TN." (PMID 37491740, 2023). "Notably, genes of tumor necrosis factor receptor superfamily TNFRSF9, TNFRSF18, and TNFRSF4 were highly and exclusively expressed in the Tregs infiltrating the tumor." (PMID 36750562, 2023). "Effector genes such as GZMB, GZMH and KLRG1 were the marker genes in clonotypes shared by all tissues, while the clonotypes present only in tumor showed upregulated T-cell exhaustion genes (HAVCR2, LAG3, CTLA4, TIGIT, PDCD1, and ICOS) and activation genes (SELL and TNFRSF9)." (PMID 36185254, 2022). "TUBA1B was overexpressed in NSCLC PBL T cells, C14 CD4/CD8 T cell clusters, and activated tumor Tregs of CD4-C9-CTLA4 (TNFRSF9+) vs. non-activated tumor Tregs of CD4-C9-CTLA4 (TNFRSF9−)." (PMID 35804895, 2022). "Moreover, ACP5, MAGEH1, TNFRSF9 and CCR8 were especially populated in tumor-infiltrating Tregs and IKZF2 was only highly expressed in paratumor-infiltrating Tregs." (PMID 35562760, 2022). "However, a higher expression of CD27, TNFRSF13C, and TNFRSF9 and a lower expression of EDA in tumours indicated better prognosis." (PMID 35392242, 2022). "Curiously, TNFSF9 (4-1BB-L) was present at a surprisingly high abundance in ACC when compared to that of other TCGA tumor types, but not its receptor TNFRSF9 (4-1BB), which was present mainly on CD8+ T cells." (PMID 34194394, 2021). "CD4+ naive T cells (cluster 0 and cluster 2) at the core of the tumor express more immune checkpoint molecules, such as CTLA4, which has been used in clinical practice, and LAG3, HAVCR2, and TNFRSF9/CD137, which are currently undergoing clinical trials than those at other locations." (PMID 34513820, 2021). "Validation of several identified mRNA species by real-time qPCR confirmed the downregulation of the proangiogenic Cyr61and Pgts2 as well as the proinflammatory Cox2 and Tnfrsf9 transcripts and the upregulation of a vessel-stabilizing factor Pdgfa in HIF-1α-KD tumor cells." (PMID 33142239, 2020). "Interestingly, a small subset of genes enriched in tumor Treg cells such as CTLA4, TIGIT, TNFRSF9, CD27, and LAYN are also highly expressed by exhausted tumor‐infiltrating CD8+ T cells reflecting a shared program of activation and exhaustion in these cells." (PMID 32272497, 2020). "Notably, tumor necrosis factor receptor superfamily member 9 (TNFRSF9), a known activation marker for antigen-specific Tregs, exhibited a striking bimodal expression distribution within tumor-infiltrating Treg cells." (PMID 32425930, 2020). "In addition, factors inducing inflammatory responses, like Peli1, Pgts2, Socs3, and Tnfrsf9, were downregulated, while an inhibitor of the NF-κB pathway (Nfkbie) was upregulated in HIF-1α-KD tumor cells." (PMID 33142239, 2020). "However, in contrast to our expectations, the expression of TNFRSF9 was found to be greater in CC tumor tissues than in myoma patient cervix (nontumorous) tissues, as validated by IHC." (PMID 38903179, 2024). "Indeed, CD8+ T cells in the tumor periphery showed increased expression of genes belonging to costimulatory pathways, including ICOS, TNFRSF4 (OX40) and TNFRSF9 (4-1BB), albeit accompanied by high levels of inhibitory receptors PDCD1 (PD-1), LAG3, HAVCR2 (TIM-3), and CTLA4." (PMID 38127790, 2023). "Furthermore, in situ detection of the corresponding genes, TNFRSF9, IFNG and TNF, may also be considered as a strategy to rapidly and efficiently identify the functional characteristics of most tumor-specific TILs based on scRNA sequencing data." (PMID 36451828, 2022).
tumor (continued). "We deduced that it may be possible to reverse T cell dysfunction by intervention in these pathways to revive CD8+ T cells against tumor activity (such as TIGIT, TNFRSF9, CTLA-4, LAG3, PD-1), and this approach maybe represented new strategies for immunotherapy against LUAD." (PMID 36483553, 2022). "Although studies have shown that the high infiltration of FOXP3+Helios− Tregs and TNFRSF9+ Tregs in tumors are not conducive to the prognosis of patients, the function and mechanisms of these subtypes of Tregs in tumor‐related immune suppression need to be further investigated." (PMID 35474948, 2022). "To verify whether the expression of TNFRSF9, TNF, and IFNG could identify all TILs actively engaged in tumor recognition in situ, we re-analyzed multiple scRNAseq datasets using fresh tumor biopsies and applied the activation gene sets as a proxy of presumed ongoing antigen stimulation in the TME." (PMID 34707600, 2021). "These genes were defined as the tumor reactive signature (TRS), including co-inhibitory receptors (CTLA4, PDCD1, TIGIT and HAVCR2), reactive markers (CD38 and ENTPD1), effector molecules (NKG7 and PRF1), tumor necrosis factor TNFRSF9 and critical exhaustion-related regulator TOX." (PMID 34804045, 2021). "Of note, the simultaneous in situ detection of the corresponding genes, TNFRSF9, TNF, and IFNG, could represent a rapid and effective strategy for the identification and future functional characterization of the majority of the tumor-specific reactive TIL repertoire in scRNAseq data." (PMID 34707600, 2021). "Moreover, the upregulation of TNFRSF1B, TNFRSF8, TNFRSF9, and TNFRSF10 expression, as well as elevated levels of TNF, suggested apoptotic signal transition through the TNF family membrane receptors, which was also detected in tumour cells treated with chemotherapeutic drugs." (PMID 35804353, 2022). "Identified as a characteristic marker of tumor-reactive T cell subsets within the tumor microenvironment (TME), TNFRSF9 is notably absent on static T cells present in peripheral blood." (PMID 38720108, 2024). "The importance of a co-stimulatory domain for anti-tumor activity was demonstrated by comparing CAR-T cells with and without TNFRSF9 signaling domains targeting CD19." (PMID 32050611, 2020).
cancer (297 papers, 2010 to 2026). A tumor composed of atypical neoplastic, often pleomorphic cells that invade other tissues. "The findings indicate that the association of CD47 and TNFRSF9 with CD8 + Tex in pan-cancer suggests their involvement in the dysregulation of CD8 + Tex in this type of cancer." (PMID 38720108, 2024). "For instance, increased expression of LCK, ITGA5, CGH1 and TNFRSF9 was associated with increased drug sensitivity of cancer cells to ribavirin, nelarabine, zalcitabine, bleomycin, asparaginase, dexrazoxane, palbociclib, etc." (PMID 38903179, 2024). "In particular, the T cell activation genes Rac2 and Igf1 were increased while the malignant tumor-associated genes Mgl2, Tnfrsf9, Vegfa as well as the M2 macrophage markers Retnla and Arg-1 were decreased." (PMID 37925462, 2023). "4-1BB (CD137/TNFRSF9), a type I transmembrane glycoprotein, is known as a T cell-associated molecule that is required for sufficient T cell immunity against cancer and infectious diseases." (PMID 35011724, 2022). "Another inflammatory-related marker increased in r-axSpA patients was TNFRSF9, which is involved in the modulation of inflammation and its dysregulation has been linked to various pathological conditions, including cancer, chronic viral infections, and autoimmune disorders." (PMID 38449853, 2024). "In addition, tumor necrosis factor receptor superfamily member 9 (TNFRSF9) was significantly associated with the development of malignancies during a 5-year follow-up period (pvalue<0.005)." (PMID 36157576, 2022). "Specifically, an increase in CD4+ TNF receptor superfamily Member 9 (TNFRF9+) regulatory T cells was observed in cancers such as iCCA, ccRCC, and BCC following ICB therapy." (PMID 40054456, 2025). "This dual role highlights the potential of TNFRSF9 as a target for reversing T-cell exhaustion and improving cancer therapy outcomes." (PMID 40236693, 2025). "The high expression levels of CD47 and TNFRSF9 in cancer cells and their correlation can be demonstrated through multiple immunofluorescence staining." (PMID 38720108, 2024). "CD8+ cytotoxic T cells had elevated expression of the cytotoxic markers PD-1, Gzmb, Gzmk, Prf1, Nkg7, Eomes, Irf8, Klrd1, Fyn, Nfatc1, Tnfrsf9, and Zap70, supporting their killing function against cancer cells." (PMID 37762216, 2023). "Patients with high TNFRSF9 were less likely to have lymphoid metastasis (p=0.0007) and lower malignant tumors (TNM) stage (p=0.0016)." (PMID 35799609, 2022). "4-1BB (TNFRSF9) is another attractive cancer immunotherapeutic target in the TNF family, which is a co-stimulatory receptor expressed on activated T cells and NK cells." (PMID 35000592, 2022). "The qRT-PCR results of the clinical samples also showed that the mRNA expression of CD27, TNF, TNFRSF12A, TNFRSF13C, and TNFRSF9 is upregulated in cancer tissues, except EDA whose mRNA expression is downregulated in cancer tissues." (PMID 35392242, 2022). "TNFRSF9 is an immune costimulatory receptor expressed on activated T- and natural killer (NK) cells and has been proposed as a new target for cancer immunotherapy." (PMID 36157576, 2022). "Of note, Patient 5, who experienced the shortest progression-free survival at 1.4 months, had the highest percentage of CTCs positive for the TNFRSF9 marker, indicating that this gene may play a significant role in cancer cell survival." (PMID 39483900, 2024). "Many researches show that anti-TNFRSF9 antibodies can boost cancer immunotherapies." (PMID 35799609, 2022). "Tnfrsf9 is known to stimulate T cells and induce strong anti-cancer and anti-autoimmune effects." (PMID 35992167, 2022). "TNFRSF9 is an important check point in cancer immunotherapy." (PMID 35646692, 2022). "Thus, this study expands the clinical application of TNFRSF9 expression in TI-Tregs as a potential biomarker in anti-PD-1 cancer immunotherapy." (PMID 33598101, 2021).
cancer (continued). "Among 60 ICP genes, including 24 immune inhibitors (such as CTLA4, LAG3, or VEGFB) and 36 activators (TNFRSF9, CD28, or TNFRSF9, etc.), we found DHCR7 played roles both in inhibitors and activators of ICP in human cancers." (PMID 41198144, 2025). "A study analyzing 21 human cancer types via scRNA-seq revealed that CD4+ T cells in tumors commonly undergo differentiation into IFNG+ Tfh/Th1 dual-functional cells and TNFRSF9+ Treg cells." (PMID 40634636, 2025). "Further analyses showed that these high HLA‐DR+ cancer cell tumors exhibited elevated levels of LAG3, TNFRSF9, CTLA4, PDCD1, TIGIT, ITGB2, and GZMB." (PMID 40464412, 2025). "Assessing the temporal secretion of 34 cytokines (including TNF-alpha) and 15 immune checkpoint proteins (including TNFRSF9 and TNFSF9), we generate the most comprehensive ZIKV-infected cancer cell secretome to date." (PMID 40240536, 2025). "We next identified cells expressing the receptors CXCR6 and TNFRSF9, which correspond to their ligands CXCL16 and TNFSF9 in Carcinoma 3, particularly in SCC." (PMID 40776410, 2025). "They markedly expressed co-stimulatory molecules (e.g., TNFRSF4, TNFRSF9, TNFRSF18), adhesion, and IFN response signatures in the very late stage of cancer." (PMID 38645221, 2024). "We explore further the gene regulatory network of PID CD8 TCR Downstream Pathway, we discovered that TNFRSF9 and CD8A were expressed at a high level in above all cancers." (PMID 38720108, 2024). "CD137 (4-1BB/TNFRSF9), an inducible costimulatory receptor, has recently received increasing attention as a therapeutic target for cancer therapy." (PMID 37226226, 2023). "The two proteins, TNFRSF9 and TNFSF9, play multiple roles in a variety of cancers, autoimmune, infectious and inflammatory diseases, mediating complex immune responses." (PMID 35894206, 2022). "Regarding receptors, there exhibited a strong correlation with PD-1 and receptors including TIGIT, CTLA-4, LAG3, BTLA, ICOS, TNFRSF9, CD27 in most types of cancer." (PMID 30607140, 2018). "T-cell co-stimulatory receptors that belong to the tumor necrosis factor receptor superfamily (TNFRSF), including OX40 receptor (CD134; TNFRSF4), 4-1BB (CD137; TNFRSF9), and glucocorticoid-induced TNFR-related (GITR) protein (CD357; TNFRSF18), are potential targets for cancer immunotherapy." (PMID 38526805, 2024). "Drugs targeting TNFRSF9, IL2RA, FCGR2A, IFNGR2 were found to be potential targets for cancers." (PMID 36857861, 2023). "In diverse cancer types, the correlation between OAS3 and the expression of checkpoint genes indicated a high correlation with TNF-related immune genes including TNFRSF14, TNFRSF8, TNFRSF25, TNFRSF4, TNFRSF18, TNFSF15, and TNFRSF9." (PMID 35592250, 2022). "Upregulated genes included members of the tumor necrosis factor superfamily (TNFRSF9, TNFRSF11B, and TNFSF8), ABC transporters (ABCB1 and ABCG2), and nuclear factor (NF)-κB-related genes (NFKB2 and RELB), all of which induce stemness in cancer cells." (PMID 28423353, 2017). "However, as stated in previous studies, the significance of TNFRSF9 in cancer is not clear, but it was suggested to be immunosuppressive." (PMID 35646692, 2022). "In multiple immune cell subsets, TNFRSF9 (CD137) provides a costimulatory signal, suggesting that combination therapy comprising CD137 antibodies with therapeutic antibodies and/or vaccination might improve cancer treatment." (PMID 33987093, 2021). "However many other conventional immune checkpoints such as TIGIT, TNFRSF4 (OX40 receptor/CD134), TNFRSF9 (4-1BB/CD137), and TNFRSF18 (GITR) are not universally overexpressed in cytotoxic CD4+ T cells from cancer patients." (PMID 34910940, 2021).